CDK6 (cyclin dependent kinase 6)
Diseases named in the same sentence as CDK6 in open-access papers (continued):
Sharing a sentence is not in itself a finding about the gene and the disease.
gastric cancer (continued). "Therefore, NCAPD3 knockdown may inhibit CCND1, MYC, and ESR1 expression to downregulate CDK6 and IRSI expression, thereby inhibiting the proliferation of gastric cancer cells." (PMID 38711992, 2024). "Therefore, NCAPD3 knockdown may inhibit CCND1 and ESR1 expression to downregulate CDK6 and IRSI expression, thereby inhibiting the proliferation of gastric cancer cells." (PMID 38711992, 2024). "Therefore, NCAPD3 knockdown may inhibit CCND1, MYC, and ESR1 activity to downregulate CDK6 and IRS1 expression, thereby inhibiting the proliferation of gastric cancer cells." (PMID 38711992, 2024). "Advanced gastric cancer (GC) is a lethal malignancy, harboring recurrent alterations in cell cycle pathway, especially the CDKN2A-CDK4/CDK6/CCND1 axis." (PMID 36755269, 2023). "Additionally, ANRIL has been found to epigenetically silence miR-99a and miR-449a via PcG complexes, promoting the CDK6/E2F1 pathway and establishing a positive feedback loop for its own expression, continuing, therefore, to promote gastric cancer cell proliferation." (PMID 37627188, 2023). "MiRNA 129 has been reported to have great potential as a therapeutic agent in select tumors including bladder cancer, colorectal cancer, gastric cancer, and lung cancer, and may inhibits cancer cell proliferation, metastasis and invasion through targeting relevant genes such as ETS1, CDK6, PAK5." (PMID 27050373, 2016). "This suggests that RCC2 and PPIC may be the target of miR-29c in gastric carcinoma, whereas CDK6 may not." (PMID 23442884, 2013). "Indeed, the expression of CDK4, CDK6 and cyclin D1, which are expressed predominantly in the G1 phase and promotes the transition to S phase of the cell cycle, closely correlated with the expression of YES1 and YAP1 in gastric cancer cells and tumor xenografts." (PMID 35017464, 2022). "In contrast to the previous observation that lncRNA GAS5 decreases CDK6 mRNA and protein levels in bladder cancer, our results indicate that lncRNA GAS5 knockdown reduced the YBX1 protein level without affecting its transcription in stomach cancer." (PMID 25959498, 2015).
melanoma (68 papers, 2006 to 2026). A malignant, usually aggressive tumor composed of atypical, neoplastic melanocytes. "miR-200 family members act by targeting several mRNAs associated with cancer cell proliferation.58miR-200a targets Cyclin-Dependent Kinase 6 (CDK6) in melanoma and thus causes cell-cycle arrest and decreases cancer cell proliferation." (PMID 39907412, 2025). "MiR-200a targets Cyclin-Dependent Kinase 6 (CDK6) in melanoma and thus causes cell-cycle arrest and decreases cancer cell proliferation." (PMID 36158660, 2022). "For example, dual inhibition of CDK4 and CDK6 has little clinical impact on colorectal cancer and melanoma, as other CDKs such as CDK1–3 compensate for the loss of CDK4 and CDK6." (PMID 35884441, 2022). "Notably, the anti-proliferative effect of REDD2 was comparable to that of the expression of CDKN2A-p16; a well-established tumor suppressor, which blocks the cell cycle by inhibiting CDK4 and CDK6 and is frequently deleted or mutated in melanoma." (PMID 40918647, 2025). "Although p16 may interact with both CDK4 and CDK6, p16 inhibition of CDK4 may be more important than CDK6 given that some melanoma-prone families have inherited activating mutations in CDK4, while none with activating CDK6 mutations have been described." (PMID 28915557, 2017). "They showed that treatment of cells with both drugs reduce the expression levels of cyclin D1, CDK4 and CDK6 in melanoma cells, and their results are consistent with those of our study." (PMID 41373567, 2025). "Similar to the increase of FRA1 in melanoma cells compared to wildtype or BRAF-mutant melanocytes, AXL, CDK6, and Fascin levels are increased in melanoma cells, especially in cells exhibiting high levels of FRA1." (PMID 41286309, 2025). "The knockdown of CDK6 sensitized melanoma cells to palbociclib, and binding was observed only when CDK6 was in its normal conformation, associated with the CDC37-HSP90 chaperone complex." (PMID 40282469, 2025). "The PTEN/AKT/mTORC1/FRA1 signaling axis we previously identified now extends to the regulation of AXL, CDK6, and FSCN1, suggesting that PTEN loss promotes melanoma metastasis partly through this mechanism." (PMID 41286309, 2025). "Recently, it has been shown that IFN‐γ induces STAT1‐dependent upregulation of miR‐29, which reduces CDK6 expression and induces G1‐arrest in melanoma cells." (PMID 39575303, 2024). "After ASNS knockout, the cyclin‐dependent kinase (CDK4), cyclin‐dependent kinase (CDK6), and cyclin D1 significantly downregulated in melanoma cells, which decreased cell proliferation." (PMID 39210809, 2024). "We conclude that dysregulation of CDK6 by JUN mediates resistance to BRAF inhibition in melanoma cells." (PMID 32413516, 2020). "Clinically, melanoma patients classified with high CDK6 signature experienced shorter PFS than patients with low CDK6 signature." (PMID 32413516, 2020). "The miRNA let-7 family, a well-established tumor suppressive ncRNA, has been found to be downregulated under ionizing radiation-induced oxidative stress, leading to the expression of CDK6 and subsequently promoting cell cycle progression of melanoma cells." (PMID 35006436, 2020). "A high CDK6 signature score was correlated with the worse PFS of melanoma patients in both clinical cohorts." (PMID 32413516, 2020). "High level of CDK6 signature was correlated with poor PFS of melanoma patients treated with either BRAFi alone or BRAFi plus MEKi." (PMID 32413516, 2020). "In this study we identify CDK4 and CDK6 as regulators of cell-proliferation, migration and tumor-angiogenesis in melanoma." (PMID 30858922, 2019). "Bioinformatic analysis of human melanoma patient data verifies the key role of CDK6 in tumor angiogenesis in melanoma." (PMID 30858922, 2019). "The fact that EZH2 as downstream factor of CDK6 was shown to regulate angiogenesis in melanoma indicates that additional angiogenic factors are involved in the CDK6 mediated angiogenesis program." (PMID 30858922, 2019).
melanoma (continued). "We add a further layer of complexity; both CDK4 and CDK6 are important in melanoma and their crosstalk regulates cell proliferation, viability, migration and angiogenesis." (PMID 30858922, 2019). "Prompted by pronounced effects of the CDK4/6 inhibitor palbociclib in melanoma xenograft studies we used specific si/sh- RNA to delete either CDK4 or CDK6 in human melanoma cell lines." (PMID 30858922, 2019). "The effects observed in melanoma were reminiscent of lymphoma models where Cdk6-/- lymphoma cells grew significantly slower paralleled by a reduced vascularization which was attributed to reduced VEGF-A expression." (PMID 30858922, 2019). "In conclusion, our data support a role for CDK4 and CDK6 as promising therapeutic targets in human melanoma." (PMID 30858922, 2019). "Effects upon CDK6 knockdown seem to be even stronger compared to CDK4 which extended to the migratory behaviour of melanoma cells in a wound healing assay." (PMID 30858922, 2019). "CDK6 knockdown in melanoma cell lines impairs VEGF-A expression and reduces the potential stimulation of endothelial cell growth." (PMID 30858922, 2019). "The CDKN2A gene is frequently mutated or deleted in melanoma tumors, leading to a release in the inhibition of cyclin-dependent kinases CDK4 and CDK6, causing a progression from G1 to S-phase and increased cell cycle activity and proliferation." (PMID 29946532, 2018). "Since the CDKN2A–CDK4/CDK6–cyclin D axis is often disrupted in melanoma CDK4/CDK6 inhibitors (e.g., abemaciclib and palbociclib) are predicted to be effective in the treatment of melanoma." (PMID 29946532, 2018). "The G1 phase arrest in the melanoma cells after their treatment with anti-miR-106b was associated with marked suppression of the expression of both cyclins and CDKs (CDK2, CDK4 and CDK6) and concomitant reactivation of p21/WAF1/Cip1 protein." (PMID 25361006, 2014). "Suppression of miR-106b in A375 and Hs294t human melanoma cells caused inhibition of cyclin D1, D2 and E, and reduction in the expression levels of CDK2, CDK4 and CDK6 proteins in both cell lines." (PMID 25361006, 2014). "This suggests that miR-29-mediated down-regulation of CDK6 is involved in decreasing proliferation rates of miR-29a/b-mimic-transfected melanoma cells." (PMID 23245396, 2012). "SiRNA-mediated knockdown of CDK6 resulted in reduced proliferation of melanoma cells similar to what has been shown for other cancer types." (PMID 23245396, 2012). "The IFN-γ-induced G1-arrest of melanoma cells involves down-regulation of CDK6, which we proved to be a direct target of miR-29 in these cells." (PMID 23245396, 2012). "Luciferase activity, as compared to the respective negative control, dropped by ~60 % for both time points in A375 melanoma cells when the CDK6 3’-UTR construct was co-transfected with miR-29a mimic." (PMID 23245396, 2012). "Here, we describe for the first time that CDK6 is a direct target of miR-29 involved in regulating growth behavior of melanoma cells." (PMID 23245396, 2012). "In line with this, we show anti-proliferative effects of miR-29 and confirm for the first time CDK6 as a direct miR-29 target in melanoma cells." (PMID 23245396, 2012). "p16INK4a is a highly penetrant melanoma tumour suppressor that regulates cell cycle progression by inhibiting the kinase activities of cyclin D-associated CDK4 and CDK6 (Serrano etal., 1993)." (PMID 18843795, 2008). "Recently, the growth of melanoma cell lines has been successfully retarded in vitro by down-regulating their CDK6 gene expression with small interfering RNA." (PMID 17177999, 2006). "Together, these papers suggest that strategies to decrease CDK6 levels in melanoma may improve response to CDK4/6is." (PMID 40282469, 2025).
melanoma (continued). "In addition to the impact on chemotherapy response, CDK6 has been shown as a master regulator of the immune resistance programme in melanoma and inhibition of CDK6 represses the resistance programme and improves responses to ICB in vivo." (PMID 38212482, 2024). "Interestingly, the PI3K-Akt signaling pathway shared all genes enriched in melanoma pathway (e.g., CDK6, FGF20, and MITF) and included three additional genes (i.e., RPTOR, COMP, and CDC37), suggesting a higher level of significance and potential relevance." (PMID 37829282, 2023). "The CDK4/CDK6 pathway is frequently dysregulated in melanoma, leading to excessive proliferation." (PMID 36765875, 2023). "A recent study demonstrated that CDK6 is upregulated in PCa and could be a potential therapeutic target as it was also described in other cancers such as bladder, melanoma, or pancreas." (PMID 37978493, 2023). "Finally, blockage of CDK4/CDK6 kinases, which were part of the resistance program, inhibited melanoma cells growth in vitro and in vivo in a melanoma mouse model." (PMID 33535416, 2021). "Overall, these observations suggest that CDK6 up-regulated by TFs JUN and ETV5 might be associated with BRAFi resistance in melanoma patients." (PMID 32413516, 2020). "While a mutant form of CDK4 associated with insensitivity towards the inhibitory INK4 proteins is found in familiar melanoma, no mutations have been identified so far in CDK6." (PMID 33255177, 2020). "Another study reported that the T cell exclusion signature was predictive of poor ICB response, however, CDK4 and CDK6 inhibitors could reverse this signature to get a better response in in vitro experiments in melanoma." (PMID 32091408, 2020). "In addition, the balanced expression of CDK4 and CDK6 is crucial to allow CDK6 to act as transcriptional regulator as has been shown in melanoma cells." (PMID 33255177, 2020). "To investigate whether CDK4 or CDK6 are also involved in cell migration in melanoma we performed scratch assays with the 518A2 and LNM1 stable shRNA clones." (PMID 30858922, 2019). "The results so far suggest that pro-angiogenic effects are not only mediated by CDK6 in melanoma but that CDK4 may also be involved." (PMID 30858922, 2019). "To further test whether CDK4 and CDK6 knockdown reduces secretion of pro-angiogenic factors we examined the effect of supernatant secreted by melanoma cells on the proliferation of human endothelial cells (HUVECs)." (PMID 30858922, 2019). "This predicts a potential role for CDK6 in metastasis in melanoma." (PMID 30858922, 2019). "In summary our data point at a role for CDK4 and CDK6 in controlling angiogenesis in melanoma." (PMID 30858922, 2019). "Knockdown of CDK4 in YU2 melanoma cells was associated with reduction in phosphorylated Rb without significantly affecting levels of total Rb or CDK6." (PMID 28915557, 2017). "Moreover, CDK4 and CDK6 have been proved to be overexpressed in cutaneous melanoma, which suggests a possible role in melanoma development." (PMID 22419847, 2012). "Similarly, CDK6 protein expression was reduced by FAK-I treatment in the human melanoma cell lines." (PMID 35525274, 2022). "Comprehensive multi-omics integration revealed transcriptional target genes of FRA1, with AXL, CDK6, and FSCN1 exhibiting increased expression in melanoma metastasis and a significant correlation with poor patient outcomes." (PMID 41286309, 2025). "Analysis of the melanoma TCGA dataset revealed that concurrent alterations of AXL, CDK6, and FSCN1 correlate with poor outcomes of melanoma patients." (PMID 41286309, 2025). "A recent study proposed a role for elevated CDK6 expression in the intrinsic resistance of NSCLC and superficial spreading melanomas to CDK4i/6i, however, we find the opposite in ALM models whereby CDK6 expression directly trends with CDK4i/6i efficacy." (PMID 38066089, 2024).
melanoma (continued). "Some proteins involved in cell cycle regulation were also investigated due to these differences: decreased levels of cyclin-dependent kinase 6 (CDK6) as well as p18, p21, and p27 were observed in both resistant melanoma cell lines versus control cells." (PMID 39175042, 2024). "Cyclin D1, CDK6, and CDK4 are significantly downregulated in human melanoma cells after ASNS depletion while p21, a CDK inhibitor, is obviously upregulated in response to ASNS knockdown." (PMID 34540668, 2021). "Through loss-of-function screens, transcriptomics, and epigenetic profile analysis, we have identified a network that includes CDK6, ETV5, and JUN as the potential mechanism for BRAFi-resistant melanoma cells." (PMID 32413516, 2020). "Likewise, 5-aminolevulinic acid-mediated sonodynamic therapy (ALA-SDT) treated melanoma cells showed increased intracellular ROS levels and miR-34a expression, which acted synergistically to inhibit the expression of pro-proliferative factors Cyclin D1 and CDK6 to suppress cell cycle progression." (PMID 35006436, 2020). "We identify the JUN family transcription factors and the ETS family transcription factor ETV5 as key regulators of CDK6, which together enable resistance to BRAF inhibitors in melanoma cells." (PMID 32413516, 2020). "To be able to assign distinct roles to CDK4 and CDK6 for melanoma formation, we performed transient siRNA as well as stable shRNA mediated knockdown of CDK4 and CDK6." (PMID 30858922, 2019). "Knockdown of RTL1 in melanoma cells resulted in cell proliferation suppression; cell cycle arrest at G1 phase; and down-regulation of E2F1, CYCLIN D1, cyclin-dependent kinase 6 (CDK6) and c-MYC." (PMID 29285312, 2017). "In both studied melanoma cell lines expression of cyclins D1 and D3, cyclin-dependent kinases CDK4 and CDK6 were observed." (PMID 29214525, 2017). "Moreover, we provide evidence for the tumor-suppressing properties of miR-29 family members: inhibition of melanoma cell proliferation could be mediated by miR-29a, which down-regulated CDK6 (cyclin-dependent kinase 6), an important player in cell cycle G1/S transition." (PMID 23245396, 2012). "Taken together, these findings indicate that both CDK6 and PI3KR1 3’-UTRs are directly targeted by miR-29 in melanoma cells; however, only CDK6 suppression seems to be important in a cellular context." (PMID 23245396, 2012). "We next examined whether FRA1 promotes melanoma metastasis via transcriptionally activating AXL, CDK6, and Fascin expression." (PMID 41286309, 2025). "Furthermore, pharmacological inhibition of CDK6 and FSCN1, and to a lesser extent AXL, suppressed melanoma metastasis and prolonged overall survival." (PMID 41286309, 2025). "Another study revealed that combined exposure of melanoma cells to metformin (1 mM) and binimetinib (2 μM) showed a reduced number of cells undergoing S phase replication compared to the control and led to G0/G1 arrest through the cyclin D/CDK4/CDK6 pathway." (PMID 41373567, 2025). "Moreover, silencing AXL, CDK6, or FSCN1 significantly reversed the stimulation of melanoma cell invasion by FRA1." (PMID 41286309, 2025). "AXL, CDK6, and Fascin did not specifically correlate with the stage of the melanomas from which these cell lines were derived, while MITF expression negatively correlated with FRA1 and its targets." (PMID 41286309, 2025). "Mir-137 can inhibit the migration and invasion of melanoma cells 45–47 by targeting various mRNAs such as PIK3R3, TBX3, c-Met, YB1, EZH2, and MITF, and inhibit the proliferation and promote the apoptosis of melanoma cells by competitive binding to genes such as SLC1A5, GLO1, CDK6, etc.." (PMID 33194692, 2020). "Additional evidence that CDK6, ETV5, and JUN may confer resistance to BRAF inhibition comes from our analysis of two independent melanoma cohorts." (PMID 32413516, 2020).